RNU6-793P (RNA, U6 small nuclear 793, pseudogene)
Gene: Small nuclear RNA gene on chromosome 6 (14,646,535 to 14,646,638, forward strand). Ensembl gene ENSG00000206960.
Homologues: Orthologues: chimpanzee U6 (97% identical), macaque U6 (95% identical). Paralogues in human: RNU6-1152P (88% identical), RNU6-211P (88% identical), RNU6-1145P (88% identical), RNU6-128P (88% identical), RNU6-1316P (88% identical), RNU6-15P (87% identical), RNU6-188P (87% identical), RNU6-20P (87% identical), RNU6-310P (87% identical), RNU6-35P (87% identical), RNU6-434P (87% identical), RNU6-589P (87% identical), and 1287 more.